HNF4A (hepatocyte nuclear factor 4 alpha)
Diseases named in the same sentence as HNF4A in open-access papers (continued):
Sharing a sentence is not in itself a finding about the gene and the disease.
pancreatic cancer (continued). "To further elucidate the clinical significance of HNF4A in pancreatic cancer, we correlated its expression with patient survival." (PMID 39165427, 2024). "We identify Hepatocyte Nuclear Factor 4A (HNF4A) as a novel target of hypermethylation in pancreatic cancer and demonstrate that site-specific proximal promoter methylation drives HNF4A transcriptional repression." (PMID 39165427, 2024). "Taken together, our data strongly suggest that HNF4A expression declines from the early stages of human pancreatic cancer; its suppression is sustained during pancreatic cancer progression and confers to poor patient survival." (PMID 39165427, 2024). "Building on our in vitro findings, we examined the HNF4A functional role in xenograft mouse models of pancreatic cancer." (PMID 39165427, 2024). "As evidenced in both the KPC mouse model and human pancreatic cancer tissues, HNF4A expression declines significantly in the early stages of the disease." (PMID 39165427, 2024). "These experiments support the notion that DNA methylation affects HNF4A expression in pancreatic cancer and most importantly identify the specific promoter loci manifesting direct HNF4A transcriptional regulation." (PMID 39165427, 2024). "In this study, we have performed a global DNA methylation analysis, in pancreatic cancer patient tissues and cell lines, and identified HNF4A as a target of hypermethylation." (PMID 39165427, 2024). "Transient HNF4A inhibition, by 2 different siRNAs in Capan-1 and HPAF-II cell lines, revealed that pancreatic cancer cell growth is significantly induced by HNF4A knockdown (Figures A17 and A18, Table A1)." (PMID 39165427, 2024). "Our data show that at least some P1 HNF4A isoforms are expressed at comparable levels in pancreatic cancer cell lines and tissues." (PMID 39165427, 2024). "HNF4A expression and cellular/subcellular localization in pancreatic cancer has attracted attention; however, the results reported are conflicting." (PMID 39165427, 2024). "To further validate the in vivo significance, we assessed HNF4A expression at different stages of murine pancreatic cancer development." (PMID 39165427, 2024). "Overall, methylation array and targeted bisulfite sequencing data defined HNF4A as a novel target of hypermethylation and designated the pancreatic cancer-specific loci of HNF4A methylation." (PMID 39165427, 2024). "To further elucidate the clinical significance of HNF4A in pancreatic cancer, we correlated its expression with patient overall survival." (PMID 39165427, 2024). "Scoring of the immunostained tissues revealed a statistically significant suppression of HNF4A in human pancreatic cancer, when compared to normal." (PMID 39165427, 2024). "In vitro and in vivo studies reveal that HNF4A is a novel tumor suppressor in pancreatic cancer, regulating cancer growth and aggressiveness." (PMID 39165427, 2024). "KRAS(G12D) -driven pancreatic tumors develop after GATA6 deletion, which is accompanied by the loss of HNF1α and HNF4α." (PMID 36249028, 2022). "Abrogation of HNF4α expression inhibited the proliferation of pancreatic cancer cells and induced their apoptosis, with increased expression of the cyclin-dependent protein kinase inhibitors p21 and p27." (PMID 33462379, 2021). "HNF4α is a prognostic marker for overall survival, is required for pancreatic cancer cell proliferation and promotes resistance to gemcitabine by downregulating hENT1." (PMID 30867652, 2019). "Our results indicated that HNF4α enhances pancreatic cancer cell proliferation and promotes gemcitabine resistance by downregulating the transcription of hENT1." (PMID 30867652, 2019).
pancreatic cancer (continued). "To elucidate the function of HNF4α, we examined its role in pancreatic cancer cell proliferation, apoptosis and gemcitabine resistance." (PMID 30867652, 2019). "We found that abrogation of HNF4α expression inhibited pancreatic cancer cell proliferation and induced cell apoptosis, with increased expression of the cyclin-dependent protein kinase inhibitors p21 and p27." (PMID 30867652, 2019). "Pancreatic cancer patients with higher HNF4α expression exhibited significantly shorter overall survival compared to patients with low HNF4α expression, with a median survival time of 11.015 months vs. 17.1 months." (PMID 30867652, 2019). "In conclusion, we demonstrated that HNF4α functioned as a tumor promoter gene that was upregulated in pancreatic cancer." (PMID 30867652, 2019). "The exploration of the HNF4A interactome, its post-translational modifications, or the development of ligand-mimicking small molecules aiming at residual HNF4A activation may prove a viable approach in pancreatic cancer therapeutics." (PMID 39165427, 2024). "Furthermore, matrigel-coated transwell assays revealed that HNF4A knockdown significantly induces pancreatic cancer cell invasiveness (Figure A20)." (PMID 39165427, 2024). "Taken together, different levels of transcriptional and epigenetic regulation might determine HNF4A expression in pancreatic cancer." (PMID 39165427, 2024). "In pancreatic cancer, HNF4α deletion led to a glycolytic energy metabolism transition from typical pancreatic adenocarcinoma to squamous pancreatic cancer, in which Fructose-Bisphosphate Aldolase A (ALDOA), Hexokinase 1 (HK), and Glycogen Synthase Kinase 3 Beta (GSK3β) genes are upregulated." (PMID 36249028, 2022). "The expression of HNF4α has been found to be aberrant in pancreatic cancer cells." (PMID 33462379, 2021). "In addition, this study demonstrated that increased HNF4α expression in pancreatic adenocarcinoma was responsible for pancreatic cancer cell proliferation and promoted resistance to gemcitabine by downregulating hENT146." (PMID 33462379, 2021). "Taken together, these findings suggest that HNF4α may serve as a potential novel predictive and therapeutic target for pancreatic cancer." (PMID 30867652, 2019). "HNF4α promotes pancreatic cancer cell proliferation and reduces gemcitabine-induced cell apoptosis." (PMID 30867652, 2019). "Based on the vital role of HNF4α in PDAC prognosis, we hypothesized that HNF4α might promote pancreatic cancer cell proliferation." (PMID 30867652, 2019). "Our results indicated that HNF4α may promote cell proliferation via the cyclin pathways in pancreatic cancer, but further investigation is needed to confirm this hypothesis." (PMID 30867652, 2019). "In summary, HNF4α may play oncogenic roles and enhances pancreatic cancer cell proliferation." (PMID 30867652, 2019). "To increase the robustness of our findings, we conducted immunohistochemistry for HNF4A in a validation cohort (UCLA cohort, USA) of 145 tissue specimens from pancreatic cancer patients." (PMID 39165427, 2024). "Although Hnf4α exerts antineoplastic activity in HCC, Hnf4α was reported to act as an oncogene in gastrointestinal adenocarcinomas and pancreatic cancer, indicating multiple roles of Hnf4α." (PMID 36242914, 2022). "By silencing HNF4α in PDAC cell lines, we assessed the impact of HNF4α on pancreatic cancer cell proliferation and gemcitabine sensitivity." (PMID 30867652, 2019).
atherosclerosis (13 papers, 2009 to 2026). A disease characterized by the build-up of fatty material and calcium deposition in the arterial wall resulting in partial or complete occlusion of the arterial lumen. "HNF4A gene variants may modify and modulate hepatic lipase and lipid metabolism, resulting in a beneficial effect on atherosclerosis progression and event occurrence." (PMID 36360783, 2022). "Paradoxically, adult chow-fed mice with liver-specific knockout (KO) of HNF4α have fatty liver but striking hypolipidemia, and these HNF4α KO mice are protected from atherosclerosis." (PMID 35614477, 2022). "The HNF4A network is composed of 35 target genes, including activation of APOE which contributes to altered VLDL metabolism and increased atherosclerosis susceptibility in NAFLD." (PMID 35925965, 2022). "MiR-34a-5p indirectly regulates several hemostatic factors via decreasing the expressions of HNF4A and other mRNAs, and it was also detected as upregulated in atherosclerosis progression." (PMID 31443660, 2019). "As a transcription factor, Hnf4a regulates expression of many genes in atherosclerosis-prone aortas of mice." (PMID 24586312, 2014). "The present findings extend these concepts to the gene network level, and delineates pathways related to NF-κB and TNF that are involved in inflammation and atherosclerosis, as well as focus genes related to ubiquitin, proteasome, histone, HNF4A, insulin and APP." (PMID 23874591, 2013). "Thus, suppression of hepatic HNF4α has been proposed to prevent atherosclerosis." (PMID 35614477, 2022). "The results indicated Hnf4a, Ppara, Vdr, and Runx3 as the TFs most likely to regulate the production of these lncRNAs, and might play roles in inflammatory and metabolic processes in atherosclerosis." (PMID 27698357, 2016). "In addition, we evaluated the potential relationship between HNF1A rs1183910, LEPR rs4420065, GCKR rs1260326, NLRP3 rs12239046, IL1F10 rs6734238, PPP1R3B rs9987289, ASCL1 rs10745954, HNF4A rs1800961 and SALL1 rs10521222 polymorphisms and CV events or subclinical atherosclerosis in RA patients." (PMID 27534721, 2016).
breast carcinoma (13 papers, 2015 to 2025). "HNF4A has been described as conferring chemoresistance in other types of tumors like breast cancer, where it has been the most upregulated gene after hypoxic conditions and led to a higher Doxorubicin resistance." (PMID 32357464, 2020). "In addition, upregulation of HNF4α under hypoxia contributes to adriamycin resistance in breast cancer." (PMID 36249028, 2022). "Lower expression of Hepatocyte Nuclear Factor 4 alpha (HNFα, NR2A1) and higher expression of V-erbA related protein (EAR2, NR2F6) were associated with increased DFS in patients with the Luminal A subtype of breast cancer (p = 0.035 and p = 0.038, respectively)." (PMID 26300846, 2015). "HNF4A showed positive expression in all patients diagnosed with primary adenocarcinoma (cohort II) and was negative in all cases of primary breast carcinoma (cohort I)." (PMID 28583188, 2017). "HNF4α was overexpressed in 22 of 23 cases of primary gastric adenocarcinoma and in 15 of 16 cases of metastatic gastric adenocarcinoma, but not in 25 cases of primary breast cancer and 17 cases of metastatic breast cancer, suggesting HNF4α as a valuable biomarker." (PMID 36249028, 2022).
liver cirrhosis (13 papers, 2012 to 2024). "We found that HNF-4α-overexpressing MSCs had a better treatment effect than unmodified MSCs on liver cirrhosis." (PMID 31133062, 2019). "MSCs overexpressing HNF-4α exerted good therapeutic effects against mouse liver cirrhosis due to an enhanced anti-inflammatory effect." (PMID 31133062, 2019). "In this study, we found that MSCs overexpressing HNF-4α exerted better therapeutic effects than control MSCs against mouse liver cirrhosis by enhancing their NF-κB-dependent anti-inflammatory effect." (PMID 31133062, 2019). "Recent studies demonstrated that BMMSCs transfected with hepatocyte nuclear factor 4 alpha (HNF-4α) had a better treatment effect than untreated BMMSCs on a CCl4 liver cirrhosis model." (PMID 31671842, 2019). "In our study, we found that HNF-4α overexpression facilitated the therapeutic effect of MSCs in liver cirrhosis." (PMID 31133062, 2019). "In addition, chronic infection down-regulates the expression of liver-specific molecules such as hepatocyte nuclear factor 4 alpha (HNF4α) and miR-122, contributing to liver cirrhosis." (PMID 35681679, 2022). "Consistent with our results, a recent study reported that MSC overexpressed HNF4α could enhance the therapeutic effects on CCl4-induced mouse liver cirrhosis model by reducing inflammation and liver injury." (PMID 33097090, 2020). "Improvement of liver function was associated with upregulation of the hepatocyte differentiating factor HNF4α and downregulation of Wilms' tumor 1 (WT-1), a nuclear factor upregulated in liver cirrhosis which has been shown to mediate hepatocellular dedifferentiation." (PMID 27658043, 2016). "The expression of HNF4α was significant higher in patients with severe hepatitis B(SHB) than those with chronic hepatitis B(CHB) and liver cirrhosis(LC) (both P < 0.05), but similar between patients with CHB and LC (P > 0.05)." (PMID 22257755, 2012). "Similarly, HNF-4α-modified MSCs showed increased therapeutic effects in a liver cirrhosis mouse model, where MSC-HNF-4α positively regulated iNOS expression by activating the NF-κB signaling pathway." (PMID 32974331, 2020). "On the other hand, expression of HNF4α differs with different outcome of HBV infection, being significantly higher in patients with severe hepatitis B(SHB) than those with chronic hepatitis B(CHB) and liver cirrhosis(LC), two well-established risks factors for CHB-associated hepatocarcinogenesis." (PMID 25238230, 2014).
ulcerative colitis (13 papers, 2009 to 2025). An inflammatory bowel disease involving the mucosal surface of the large intestine and rectum. "A single nucleotide polymorphism (SNP), rs6017342, in the 3’-UTR of HNF4A causes increased susceptibility to ulcerative colitis." (PMID 37635981, 2023). "Results implicating HNF4α in IBD are bolstered by evidence from genome-wide association studies in geographically diverse cohorts of ulcerative colitis patients, which identify HNF4A as a major susceptibility locus." (PMID 37635981, 2023). "In genome-wide association studies, HNF4A was also described as a susceptibility gene for ulcerative colitis." (PMID 35132353, 2022). "In 2009, genomic-wide association scanning on 2361 cases of ulcerative colitis and 5417 control cases revealed that HNF4α was related to the progression of ulcerative colitis." (PMID 36249028, 2022). "Both HNF4A and the intestinal microbiota have been separately implicated in the pathogenesis of the human IBDs Crohn's disease and ulcerative colitis." (PMID 28385711, 2017). "Moreover, mutations in human HNF4A are associated with chronic intestinal inflammation, irritable bowel disease, ulcerative colitis, and Crohn’s disease, suggesting that these functions are conserved through evolution." (PMID 27185732, 2016). "While genome-wide association studies have identified common polymorphisms in the HNF4A gene associated with ulcerative colitis, insufficient evidence is available to determine whether rare deleterious variants in this gene increase risk for ulcerative colitis or other autoimmune disorders." (PMID 40585884, 2025). "Crohn’s disease and ulcerative colitis are the most common forms of IBD and HNF4α has been implicated in both." (PMID 37635981, 2023). "The expression of the aurora kinase A (AurkA) transcript, a regulator of mitosis that is up-regulated in patients with ulcerative colitis, was also significantly up-regulated in the long term in colon of Hnf4α mutant mice." (PMID 19898610, 2009).
non-alcoholic fatty liver disease (12 papers, 2016 to 2025). "The activation of HNF-4α induces lipophagy, which results in a release of lipids in hepatic tissue, which can alleviate non-alcoholic fatty liver disease (NAFLD)." (PMID 40364401, 2025). "At the same time, HNF4A is the core factor in the pathogenesis of nonalcoholic fatty liver disease (NAFLD)." (PMID 35132353, 2022). "HNF4α has been shown to be upregulated in nonalcoholic fatty liver disease (NAFLD)." (PMID 35203271, 2022). "These proteins were mainly involved in fatty acid metabolism (Fasn, Scd1, Fads2, Fdps, Plin2), fatty acid degradation (Ehhadh, Acsl1), PPAR signaling pathway (Fads2, Ehhadh, Acsl1, Fabp1), non-alcoholic fatty liver disease (Ehhadh, Pklr) and AMPK signaling pathway (Fasn, Scd1, Hnf4a)." (PMID 32210812, 2020).